HMGA2 (high mobility group AT-hook 2)
Diseases named in the same sentence as HMGA2 in open-access papers (continued):
Sharing a sentence is not in itself a finding about the gene and the disease.
head and neck squamous cell carcinoma (12 papers, 2007 to 2023). A squamous cell carcinoma that arises from any of the following anatomic sites: lip and oral cavity, nasal cavity, paranasal sinuses, pharynx, larynx, and salivary glands. "A correlation between miR-98 and chemoresistance that is associated with the downregulation of HMGA2 was found in head and neck squamous cell carcinoma, providing the first link between miR-98 levels and HMGA2 expression." (PMID 31979076, 2020). "It has been reported that let-7b-5p inhibits migration, invasion, and EMT by targeting HMGA2 in head and neck squamous cell carcinoma and HCC cells." (PMID 37019900, 2023). "HMGA2 expression was shown to be partly regulated by the let-7 miRNA family member mir-98 in head and neck squamous cell carcinoma cell lines." (PMID 25245141, 2014). "Here we report that HMGA2 expression in head and neck squamous cell carcinoma (HNSCC) cells is regulated in part by the expression of miRNA-98 (miR-98)." (PMID 17222355, 2007). "Finally, we have shown that, HMGA2 expression was decreased dramatically in gefitinib‐resistant cells, as well as in erlotinib‐resistant head and neck squamous cell carcinoma cells." (PMID 29901268, 2018). "Furthermore, Hebert and co-workers have reported that HMGA2 (High Mobility Group A2) expression in head and neck squamous cell carcinoma (HNSCC) cells are regulated by the expression of miR-98." (PMID 23211491, 2012). "Here we report that HMGA2 expression in head and neck squamous cell carcinoma (HNSCC) cells is regulated in part by miRNA-98 (miR-98)." (PMID 17222355, 2007).
type 2 diabetes (12 papers, 2011 to 2025). "HMGA2 has been revealed to increase the risk of developing nephropathy in those patients with type 2 diabetes." (PMID 34174955, 2021). "HMGA2 is associated with aortic root size, type 2 diabetes, and many other traits like tooth development, head circumference and brain structure." (PMID 25281659, 2015). "In this analysis, we also found that HMGA2 locus was significantly associated with increased FPG in these samples, suggesting that SNPs in the MTNR1B or the HMGA2 loci confer susceptibility to type 2 diabetes in Japanese populations." (PMID 22046406, 2011). "So far, five African-American type 2 diabetes-associated signals have been reported, three of which (two in KCNQ1 and one in HMGA2) were first reported in Europeans and two (INS-IGF2 and HLA-B) were first reported in African-Americans." (PMID 31049640, 2019). "Indeed, knock-out of the Hmga1 and Hmga2 genes leads to different phenotypes: cardiac hypertrophy and type 2 diabetes in the former case, and a large reduction in body size and amount of fat tissue in the latter case." (PMID 24728959, 2014). "Gene association studies have so far identified 16 candidate loci involved in PCOS, including genes involved in gonadotropin action (LHCGR and FSHR), metabolism and sexual development (ESR1), insulin signaling and type 2 diabetes (INSR, THADA, HMGA2) or cell proliferation (YAP1 and SUMO1P1)." (PMID 40551954, 2025).
osteosarcoma (11 papers, 2004 to 2025). A usually aggressive malignant bone-forming mesenchymal neoplasm, predominantly affecting adolescents and young adults. "In summary, our study demonstrates that HMGA2 is overexpressed in the majority of osteosarcoma tissues and is associated with a worse clinical prognosis and chemoresistance for osteosarcoma patients." (PMID 35388973, 2022). "In our study, knockdown of HMGA2 increased osteosarcoma cell sensitivity to doxorubicin and cisplatin." (PMID 35388973, 2022). "To exclude the possibility of HMGA2 expression being an artifact induced by in vitro propagation, we evaluated HMGA2 expression in eight fresh osteosarcoma specimens." (PMID 35388973, 2022). "Our results indicate high HMGA2 expression is an independent predictor of poor osteosarcoma prognosis." (PMID 35388973, 2022). "HMGA2 expression was also evaluated in osteosarcoma cell lines and patient tissues by Western blot, we analyzed the expression of HMGA2 in the human osteosarcoma cell lines MG63, 143B, U2OS, Saos‐2, MNNG/HOS, and KHOS." (PMID 35388973, 2022). "HMGA2 expression was elevated in the osteosarcoma patient specimens and human osteosarcoma cell lines." (PMID 35388973, 2022). "The expression of HMGA2 in osteosarcoma patient tissue samples is evaluated by IHC staining of the TMA." (PMID 35388973, 2022). "Inhibition of HMGA2 decreased osteosarcoma cell growth and proliferation while enhancing chemosensitivity." (PMID 35388973, 2022). "Our findings suggest that HMGA2 is a novel prognostic biomarker and a promising therapeutic target in the treatment of osteosarcoma, especially when used in combination with standard chemotherapeutics." (PMID 35388973, 2022). "HMGA2‐specific siRNA and clonogenic assays were then used to determine the effect of HMGA2 inhibition on osteosarcoma cell proliferation, growth, and chemosensitivity." (PMID 35388973, 2022). "Here we evaluate the expression, clinical prognostic value, and overall function of HMGA2 in osteosarcoma." (PMID 35388973, 2022). "To determine the potential roles of HMGA2 in osteosarcoma, we analyzed the expression of HMGA2 in the human osteosarcoma cell lines MG63, 143B, U2OS, Saos‐2, MNNG/HOS, and KHOS." (PMID 35388973, 2022). "The clonogenic assays also showed a reduction in size and number of osteosarcoma colonies following the silencing of HMGA2, further suggesting the importance of HMGA2 in osteosarcoma growth and division." (PMID 35388973, 2022). "Western blot and immunofluorescent assays were performed to evaluate the expression of HMGA2 in osteosarcoma cell lines following HMGA2‐specific siRNA transfection." (PMID 35388973, 2022). "Effects of HMGA2 expression on osteosarcoma cell proliferation and growth were accessed by HMGA2‐ specific siRNA loss of function studies." (PMID 35388973, 2022). "Our study supports HMGA2 as a potential prognostic biomarker and therapeutic target in osteosarcoma." (PMID 35388973, 2022). "We therefore examined the expression of HMGA2 in osteosarcoma, its correlation with patient clinicopathology, and its roles in osteosarcoma cell proliferation and chemosensitivity." (PMID 35388973, 2022). "Our study also revealed that HMGA2 is expressed in osteosarcoma cell lines and fresh osteosarcoma tissues, with the cell lines showing a significant reduction of growth and viability following HMGA2 knockdown." (PMID 35388973, 2022). "Sixty‐nine osteosarcoma patient specimens within a tissue microarray (TMA) were analyzed by immunohistochemistry for HMGA2 expression." (PMID 35388973, 2022). "While further mechanistic study is needed, our data suggest that targeting HMGA2 in combination with commonly used osteosarcoma chemotherapeutics is a promising new treatment approach." (PMID 35388973, 2022).
osteosarcoma (continued). "We first evaluated the expression of HMGA2 in osteosarcoma patient tissue samples by IHC staining of the TMA." (PMID 35388973, 2022). "Based on patient follow‐up data, expression of HMGA2 was markedly higher in the osteosarcoma tissues of patients who later developed metastatic disease compared to those who did not (P = 0.014)." (PMID 35388973, 2022). "In osteosarcoma, HMGA2 has been reported as a mediator and miRNA target that can affect malignant cell abilities." (PMID 33762953, 2021). "CCDC144NL-AS1 also promoted the oncogenicity of osteosarcoma by acting as a molecular sponge for microRNA-490-3p and thereby increasing HMGA2 Expression." (PMID 35083139, 2021). "For instance, lncRNA CCDC144NL-AS1 facilitates the oncogenicity of osteosarcoma via acting as “sponge” for miRNA-490-3p and increasing high mobility group AT-Hook 2 (HMGA2) expression." (PMID 34965215, 2021). "High HMGA2 expression is an independent predictor of poor osteosarcoma prognosis." (PMID 35388973, 2022). "Our study shows that HMGA2 was highly expressed in 71.0% of osteosarcoma patient tissue specimens." (PMID 35388973, 2022). "Taken together, we conclude that HMGA2 may play a critical role in the osteosarcoma chemoresistance seen within the clinic." (PMID 35388973, 2022). "In addition, 39 of 48 (81.8%) of the osteosarcoma patients with metastasis showed overexpression of HMGA2, which was notably higher than the tissue specimens of patients with localized cancer." (PMID 35388973, 2022). "To validate whether HMGA2 expression held clinical significance, we assessed its correlation with osteosarcoma patient pathology and outcomes." (PMID 35388973, 2022). "Importantly, multivariate Cox regression confirmed that high expression of HMGA2 was an independent predictor of shorter overall survival in osteosarcoma patients (P = 0.006)." (PMID 35388973, 2022). "Despite its notoriety in other malignancies, HMGA2 expression, clinical significance, and potential as a therapeutic target remain unclear in osteosarcoma." (PMID 35388973, 2022). "HMGA2 was differentially expressed in human osteosarcoma cell lines." (PMID 35388973, 2022). "Furthermore, our study revealed the overexpression of HMGA2 to correlate with shorter overall survival for osteosarcoma patients." (PMID 35388973, 2022). "Although high‐mobility group AT‐hook 2 (HMGA2) has been shown to have crucial roles in the pathogenesis and metastasis of various malignancies, its expression and significance in osteosarcoma remain unknown." (PMID 35388973, 2022). "The purposes of our study are: (i) to analyze the relationship between HMGA2 and the development of osteosarcoma; (ii) to provide a theoretical basis for the reversal of chemotherapy resistance of osteosarcoma; (iii) to elucidate HMGA2 as a potential therapeutic target of osteosarcoma." (PMID 35388973, 2022). "We also applied a Cox regression analysis to determine whether HMGA2 expression was an independent prognostic factor for osteosarcoma patients." (PMID 35388973, 2022). "Our findings support the oncogenic role of LINC01116 in promoting the development of doxorubicin resistance in osteosarcoma, and LINC01116/miR-424-5p/HMGA2 axis may be a promising chemo sensitizing strategy for the treatment of osteosarcoma." (PMID 33762953, 2021). "This immunofluorescence data was consistent with our osteosarcoma TMA findings, which demonstrated that HMGA2 expression is predominantly within the nucleus as well." (PMID 35388973, 2022). "In this study, an in-depth investigation of EMT in osteosarcoma cells indicated that upregulated LINC01116 induced miR-424-5p suppression and downstream HMGA2 overexpression, which promoted the EMT process and subsequent cancer metastasis." (PMID 33762953, 2021). "In osteosarcoma, SMARCAL1, IRS1, SUB1, HMGA2, and FANCM were identified as Supertargets." (PMID 37297004, 2023).
osteosarcoma (continued). "In order to evaluate the effect of HMGA2 expression on chemosensitivity in osteosarcoma cells, MTT assays were conducted to compare the cell viability of 143B and KHOS cells treated with increasing concentrations of doxorubicin or cisplatin following HMGA2 knockdown." (PMID 35388973, 2022). "Bioinformatics analysis has revealed that HMGA2 is closely related to LINC01116; thus, we aimed to determine its expression, function, and correlation with LINC01116 to explore whether and how it can influence chemoresistance in osteosarcoma." (PMID 33762953, 2021).
sarcoma (11 papers, 2010 to 2024). A usually aggressive malignant neoplasm of the soft tissue or bone. "HMGA2 is a critical regulator in the development of some tumors, including sarcomas and rhabdomyosarcomas, generally related to bad prognoses." (PMID 36614297, 2023). "This study identifies altered HMGA2/IGF2BP/IGF2 signaling in CIC-DUX4 sarcomas and provides proof of principle for combination therapy with trabectedin and AKT/mTOR dual inhibitors to specifically combat the disease." (PMID 34903601, 2022). "Five genes are expressed only in this type of sarcoma: PIK3CA, MDM2, HMGA2, EGFR, CDK, CDK4, while CDKN2A is implicated in angiosarcomas and undifferentiated pleomorphic sarcomas only." (PMID 34359782, 2021). "To corroborate the clinical relevance of our findings, we examined the expression of LIN28B and HMGA2 in sarcoma cohort using the StarBase database." (PMID 31147574, 2019). "Our data support the clinical relevance of LIN28B and HMGA2 as possible prognostic markers and as molecular targets for novel therapeutic approaches in sarcoma." (PMID 31147574, 2019). "We suggest that amplification and truncation of HMGA2 in sarcoma provide the tumors with a more stem-like phenotype." (PMID 20576167, 2010). "To investigate these questions, we will determine the activity of truncated HMGA2 in sarcoma cells by siRNA-based knock-down in cells with the natural malignant genetic background." (PMID 20576167, 2010). "Their lost ability to present tumor antigens on their cell surfaces may contribute to their escape from immunosurveillance and therefore this might also provide a selective advantage to sarcoma cells expressing truncated HMGA2." (PMID 20576167, 2010). "In sarcomas, HMGA2 is frequently and selectively amplified and rearranged." (PMID 20576167, 2010). "A recent paper reported that HMGA2 can activate the transcription of IGF2BP, which in turn activates AKT-mTOR through the signal transduction of the IGF2-IGF1R interaction in sarcoma." (PMID 38493165, 2024). "The analysis of the collection of human cancers available from The Cancer Genome Atlas (TCGA) indicates HMGA2 and RPSAP52 expression is specially increased in adrenocortical carcinoma, mesothelioma and in the sarcoma samples available (as measured by Z-score)." (PMID 31484926, 2019). "Furthermore, using total RNA, and not DNA samples, the fusion genes of various sarcomas could be identified, such as HMGA2-LPP and TLS-CHOP, while detecting MDM2 and CDK4 overexpression by quantitative real-time PCR." (PMID 24965044, 2014). "We conclude that the c-terminal part of HMGA2 has important functions at least in mesenchymal cells, and the changes in gene expression resulting from overexpressing a protein lacking this domain may add to the malignant potential of sarcomas." (PMID 20576167, 2010).
triple-negative breast carcinoma (11 papers, 2013 to 2025). An invasive breast carcinoma which is negative for expression of estrogen receptor (ER), progesterone receptor (PR), and human epidermal growth factor receptor 2 (HER2). "We have linked HMGA2 regulation by Wnt10b/β-catenin signalling from the embryonic mammary gland anlagen to triple-negative breast cancer." (PMID 23307470, 2013). "In the case of miR-150, it has been observed to suppress metastasis in triple-negative breast cancer by targeting HMGA2 gene." (PMID 34123357, 2021). "In addition, it has been documented that β-catenin can activate EZH2 expression through synergistic interactions with HMGA2 in triple-negative breast cancer." (PMID 33823894, 2021). "Alternatively, the co-localization of nuclear β-catenin with intense Hmga2 staining in mouse tumors could reflect Wnt signaling enhancement of Hmga2 expression, a phenomenon observed in triple-negative breast cancer, a subtype that also tends to express high LIN28B levels." (PMID 26244988, 2015).
acute myeloid leukemia (10 papers, 2014 to 2025). Acute myeloid leukemia (AML) is a group of neoplasms arising from precursor cells committed to the myeloid cell-line differentiation. "It has also been reported that ectopic Hmga2 expression in adult HSPCs led to the development of acute myeloid leukemias (AML) in a Tet2-deficient context." (PMID 40143971, 2025). "HMGA2 regulated the progression and the sensitivity of acute myeloid leukemia to doxorubicin by activating the Wnt/β-catenin signaling pathway." (PMID 34856955, 2021). "Intriguingly, a recent large‐scale clinical study identified HMGA2 expression as a sole predicting marker for relapse and poor clinical outcomes in 350 acute myeloid leukemia (AML) patients receiving combinatorial treatments that targeted TOP2 and replicative DNA synthesis." (PMID 31271486, 2019).
oral cancer (10 papers, 2013 to 2024). "Considering this we aimed to detect circulating HMGA2 in liquid biopsies of oral cancer patients and to dicover its diagnostic and prognostic potential." (PMID 33639654, 2021). "This notion is further supported by our findings that positive HGMA2 staining in oral cancer cells is associated with many clinicopathological parameters (e.g., cervical metastasis), and the siRNA-mediated knockdown of HMGA2 attenuated in the migration and invasion capability of OSCC cells." (PMID 26138061, 2015). "Although some articles also showed the association between poor prognosis and HMGA2 overexpression in oral cancer, there were few studies which reported the high expression of HMGA2 in metastatic OSCC23,24." (PMID 38671227, 2024). "HMGA2 expression has been linked to malignant traits of oral cancer in tissue biopsies however, data on HMGA2 expression in liquid biopsies in oral cancer is sparse." (PMID 33639654, 2021). "Purpose of this study was to explore prognostic relevance of HMGA2 in liquid biopsies of oral cancer patients." (PMID 33639654, 2021). "The role of HMGA2, which is a mesenchym-specific factor was thus strongly correlated with poor differentiation, invasion and metastasis of oral cancer." (PMID 25245141, 2014). "Concerning human oral carcinoma, analysis of HMGA2 expression was reported to be found significantly over-expressed in carcinoma tissues when compared to non neoplastic tissues." (PMID 25245141, 2014). "Our immunohistochemical findings in canine OSCC are comparable with the findings seen in human OSCC supporting the data discussing a possible role of HMGA2 as a factor promoting cell proliferation and motility at the invasive front in canine oral cancer." (PMID 25245141, 2014). "HMGA2 was also found to be expressed at the invasive front of oral carcinomas." (PMID 33519932, 2021). "Although, some reports described the association between HMGA2 overexpression and poor prognosis in oral cancer, no other reports have identified that high HMGA2 expression contributes to distant metastasis in OSCC." (PMID 31109142, 2019). "HMGA2 was found to be expressed at the invasive front of oral carcinomas leading to the conclusion that –in contrast to HMGA1- HMGA2 immunostaining could be a potential prognostic determinant in stratifying patients into risk groups." (PMID 25245141, 2014). "Immunohistochemical localisation showed that HMGA2 protein was localised at the invasive front of oral carcinomas leading to the conclusion that HMGA2 immunostaining could be a prognostic determinant in stratifying patients into risk groups." (PMID 25245141, 2014). "The protein expression levels of endogenous HMGA2 and MIF and the effects of their siRNA-mediated silencing in two oral cancer cell lines (SCC4 and SCC25) were determined by Western blotting using anti-HMGA2 and anti-MIF antibodies." (PMID 26138061, 2015). "Differentially expressed microRNAs have been found to tightly regulate four of the possible biomarkers that we identified—HMGA2, EGFR, HOXA1, and ABCC5/ABCC4 —further supporting their involvement in oral-cancer progression." (PMID 26179909, 2015). "Although, some reports described the importance of HMGA2 in the poor prognosis of oral cancer, its precise role in OSCC has not been fully elucidated." (PMID 31109142, 2019). "The high mobility group A2 (HMGA2) protein was found to be highly expressed in human OSCC and its expression was suggested to act as a useful predictive and prognostic tool in clinical management of oral carcinomas." (PMID 25245141, 2014).